TREM1 (triggering receptor expressed on myeloid cells 1)
Diseases named in the same sentence as TREM1 in open-access papers (continued):
Sharing a sentence is not in itself a finding about the gene and the disease.
tumor (continued). "Additionally we show that tumor tissue has an increased expression of COX-2 with PGE2 production and that macrophages that are treated with PGE2 show an increased expression of TREM-1." (PMID 24842612, 2014). "In addition, we found that fibroblasts, as signal senders, may cooperate with TREM1+ PMN-MDSCs in extracellular matrix remodeling and tumor progression by secreting collagen and FN1 to interact with the CD44." (PMID 41413734, 2025). "Further investigation on ESTIMATE scores analysis implied that TREM1 expression showed positive correlation positive correlations with both stromal and immune cell content in the TME, indicating that the tumor-infiltrating immune cells (TIICs) might contribute to tumor progression." (PMID 39744496, 2025). "An agonistic TREM1 monoclonal antibody (PY159) could upregulate the secretion of inflammatory factors such as IFN-γ, CCL3, CCL4, IL-8, and TNF and increased tumor sensitivity to anti-PD-1 therapy in syngeneic mouse tumor models." (PMID 39744496, 2025). "TREM1 highly expressed in myeloid cells, maintains the tumor inflammatory microenvironment via the NF-κB/IL-6/STAT3 pathway; it may also directly activate pro-survival signals within tumor cells (e.g., PI3K-AKT)." (PMID 41415031, 2025). "In addition, TREM-1 + TAMs also respond to hypoxic conditions and tumor metabolites through the ERK/NF-κβ pathway, resulting in an increase in CCR6 + Foxp3 + Tregs, which promotes tumor immunosuppression and creates resistance to PD-L1-targeted therapies." (PMID 39068459, 2024). "However, due to the limitation of the small number of tumor tissue sections, the expression and distribution of TREM-1 and the invasion of immune cells were not simultaneously investigated." (PMID 37217993, 2023). "Although TREM-1 has not been yet extensively studied in all kind of tumor types (ie: solid as hematological malignancies), TREM-1 should be consider as a potential biomarker in human oncology and could be used as a new therapeutic target of interest." (PMID 35875168, 2022). "Taken together, both ibrutinib and acalabrutinib can inhibit TLR-BTK, TREM-1-BTK and Dectin-1-BTK signaling pathways in monocytes and macrophages, resulting in reduced production of inflammatory cytokines and chemokines as well as impaired phagocytosis of tumor cells and infectious pathogens." (PMID 34485307, 2021). "Thus, it is feasible that TREM-1 signaling in the breast TME could, through multiple different mechanisms, contribute to the blockade of specific anti-tumor immune responses." (PMID 34956864, 2021). "Thus, this balance of pro-inflammatory TREM-1 to anti-inflammatory TREM-2 might, in part, control the phenotype and function of tumor-infiltrating myeloid cells." (PMID 35223446, 2021). "Additionally, we demonstrated the presence of a TREM-2 ligand on TAM and showed that TREM-1 on MDSC was functional, suggesting that both TREMs may regulate these myeloid populations within the tumor, thus possibly balancing each other." (PMID 35223446, 2021). "Furthermore, using The Cancer Genome Atlas (TCGA) database, we found that, although not an individual predictor for survival, TREM-1 expression correlates with disease severity and tumor burden." (PMID 35223446, 2021). "Second, from our studies, we cannot rule out the possibility that TREM-1 activation may, in certain instances, promote anti-tumor immunity." (PMID 34956864, 2021). "Interestingly, PD-L1 blockade failed to improve TREM-1+TAM-mediated immunosuppression in tumor-bearing mice because of Treg recruitment by the TREM-1-induced CCL20 release in response to the hypoxic environment." (PMID 32456204, 2020). "Moreover, TREM-1 could impact various cytokines, such as IL-8, MCP-1, and TNF-α, in the tumor microenvironment." (PMID 33204302, 2020).
tumor (continued). "They compared the expression of TREM-1 on monocytes in the peripheral blood, and they found that the expression of TREM-1 on macrophages in the tumor was lower than on monocytes in the peripheral blood so the condition in the peripheral blood appears to be opposed to the tumor." (PMID 32684831, 2020). "In wildtype Trem1+/+ mice, Trem1 was expressed in tumors but not in the tumor-free adjacent mucosa." (PMID 29093489, 2017). "At the end of the observation period, myeloid cell populations in the tumor-free colon were comparable to those seen in untreated non-inflamed controls; however, neutrophils were still present at elevated frequencies, particularly in Trem1+/+ mice." (PMID 29093489, 2017). "Notably, CD46 and TREM1 may collaboratively shape a tumor-promoting microenvironment: CD46 potentially mediates immunosuppression via T-cell regulation, while TREM1 drives sustained production of pro-inflammatory factors (e.g., TNF-α, IL-6) by amplifying NF-κB signaling." (PMID 41415031, 2025). "“T cell” neighborhoods enriched with effector T cells and mature macrophages that lacked tumor epithelium lie immediately adjacent to drug-sensitive proliferating BCC surrounded by TREM2 + VCAM1+ myeloid cells or resistant BIT tumors surrounded by lymphocyte-poor TREM1+ myeloid-driven inflammation." (PMID 39289380, 2024). "Moreover, levels on monocytes/macrophages have been shown to progressively decrease with the advancement of tumor stage and tumor invasion of lymph nodes in NSCLC, supporting that low TREM-1 expression on TAMs may be new characteristic of late stage pulmonary carcinoma." (PMID 35875168, 2022). "Thus, rather than representing an activation stimulus at the tumor site, the detrimental effects of TREM1 expression revealed by our TCGA analysis may represent a secondary method of tumor immunosuppression via suppression in trans due to soluble TREM-1." (PMID 35223446, 2021). "However the mechanism by which TREM-1 is induced in tumor tissue has not been defined." (PMID 24842612, 2014). "On the other hand, phagosome formation, the tumor microenvironment pathway, LPS/IL-1 mediated inhibition of RXR function, TREM1 signaling and IL-6 signaling were categorized with negative z-score." (PMID 37047308, 2023). "The expression of TREM-1 on MDSC was not restricted to the 4T1 model or the BALB/c strain as TREM-1 was also expressed on PMN- and Mo-MDSC from EL-4 tumor-bearing C57BL/6 mice (data not shown)." (PMID 35223446, 2021). "Our study further reveals that in contrast to the reported expression of TREM-1 on macrophages in NSCLC and HCC16,27, in murine CRC tumor-infiltrating neutrophils but not macrophages express TREM-1." (PMID 29093489, 2017). "Across tumor types, the predominant TREM-1 staining pattern observed was moderate to strong TREM-1 staining in a fraction of tumor-infiltrating myeloid cells that co-expressed CD68, with negative staining in tumor cells (pattern P-1)." (PMID 34956864, 2021). "In addition, sample-wise analysis showed that the expression of TREM1, rather than GFAP or P2RY12, significantly correlated with EMT score, indicating that macrophage M2 infiltration moderately correlated with enhanced tumor stemness." (PMID 34540693, 2021). "Importantly, TREM1 expression was not detectable in GBM cell lines under normoxia or hypoxia, indicating that TREM1 expression originated from cell types other than tumor cells." (PMID 32765489, 2020). "Similarly, TREM-1 expression on neutrophils was comparable in neutrophils isolated from healthy colonic tissue of untreated control mice, AOM/DSS-induced tumors, as well as adjacent tumor-free, colonic tissues of treated mice (data not shown)." (PMID 29093489, 2017).
tumor (continued). "Finally, our results suggest that therapeutic inhibition of TREM-1 may not only prevent onset of cancer in patients with IBD, but that TREM-1 could represent a novel immunotherapeutic target to restrain cancer-promoting inflammation without jeopardizing anti-microbial and anti-tumor immunity." (PMID 29093489, 2017).
cancer (71 papers, 2009 to 2026). A tumor composed of atypical neoplastic, often pleomorphic cells that invade other tissues. "Currently, TREM-1 is well recognized as a key player in cancer and numerous other inflammation-associated diseases and disorders of infectious and non-infectious origin (reviewed in." (PMID 41404075, 2025). "TCGA data: Hypomethylation in the TREM1 gene is associated with high expression and poor prognosis in different types of cancer." (PMID 39149674, 2024). "It confirms that high TREM1 gene expression is negatively associated with overall survival rates, suggesting poor prognosis for these cancers." (PMID 39149674, 2024). "We are specifically analyzing the association of methylation promoters related to cancer while also focusing on uncovering the relationship between high expression of the TREM1 gene and methylation." (PMID 39149674, 2024). "We further analyzed the prognosis rate of ESCA, HNSC, KIRC, KIRP, PAAD, and STAD cancers associated with TREM1 gene expression (P<0.05)." (PMID 39149674, 2024). "To investigate the therapeutic potential of TREM1 in cancer, we used mice deficient in Trem1 or we treated WT mice with a novel small molecule TREM1 inhibitor, VJDT." (PMID 37651197, 2023). "To investigate the therapeutic potential of TREM1 in cancer, we used mice deficient in Trem1 and developed a novel small molecule TREM1 inhibitor, VJDT." (PMID 37651197, 2023). "Different TREM-1 inhibitors have been designed and studied in different murine models of malignancies associated with chronic inflammation." (PMID 35875168, 2022). "We analyzed the association of TREM-1 expression with pan-cancer overall survival via Gene Expression Profiling Interactive Analysis (GEPIA)." (PMID 34122331, 2021). "Increased expression of TREM-1 in TAM were reported to predict cancer aggressiveness and associated with worse treatment outcomes." (PMID 29844416, 2018). "Since chronic inflammation is closely linked to cancer we questioned if TREM-1 is expressed in NSCLC tissue." (PMID 24842612, 2014). "Moreover, pan-cancer analysis showed TREM1 was closely associated with prognosis and immune-related genes expression in various types of cancer." (PMID 39744496, 2025). "Similarly, high TREM1 expression was found to be associated with poor prognosis in multiple cancer types, including KIRC, LUSC and LGG." (PMID 41413734, 2025). "So far, however, the therapeutic use of TREM-1 inhibitors has been limited to preclinical models, and only studies designed to measure the prognostic/diagnostic value of TREM-1 expression and/or sTREM-1 levels in samples from patients with inflammation-associated cancer have been carried out." (PMID 32456204, 2020). "In the present study, we hypothesized that TREM-1 contributes to colitis-associated cancer in the azoxymethane (AOM)/DSS model of CRC." (PMID 29093489, 2017). "Therefore, we were not able to address the previously postulated association between TREM-1 and cancer progression with our in vivo model." (PMID 29093489, 2017). "Furthermore, high TREM1 mRNA expression was linked to poor prognosis in several cancers." (PMID 39149674, 2024). "Furthermore, TREM-1 expression in patients with NSCLC has been associated with cancer recurrence and poor survival of patients suggesting that TREM-1 may play an important role in cancer progression." (PMID 24842612, 2014). "In this study, we utilized a combination of CRISPR-Cas9 genome ablation of TREM1 and its pharmacological inhibition by a novel small molecule inhibitor, VJDT, to characterize the impact of TREM1 silencing in cancer cells directly." (PMID 40677705, 2025). "The clustering revealed that TREM1 expression had a significant connection with the immune score and the stromal score in pan-cancer analysis." (PMID 39744496, 2025). "Further research is needed to elucidate these mechanisms and optimize TREM-1-based therapies across different cancer types." (PMID 40917508, 2025).
cancer (continued). "In fact, preclinical studies have demonstrated that blocking TREM1 have positive effects in cancer therapy." (PMID 39744496, 2025). "Therapeutic modulation of TREM-1 has shown promise in managing a range of diseases, for example, diabetes, cancer, chronic kidney disease, cardiovascular disorders, and neurological conditions." (PMID 41226426, 2025). "Ongoing studies are focused on the determination of the therapeutic window for resolving cancer therapy-induced inflammation by macrophage-restricted TREM-1 blockade." (PMID 41404075, 2025). "These context-dependent effects underscore the importance of understanding the specific TME and the stage of cancer development when considering TREM-1 as a therapeutic target." (PMID 40917508, 2025). "TREM-1 serves as a critical regulator in a range of diseases, including neurological, cardiovascular, cancer-related, and inflammatory conditions." (PMID 41226426, 2025). "We next estimate the link between TREM1 expression and immune checkpoints in pan-cancer, and a strong correlation was revealed in multiple types of cancers." (PMID 39744496, 2025). "This has significant implications for clinical strategies targeting TREM-1, particularly informing tailored treatment approaches for cancer and inflammatory diseases." (PMID 41404075, 2025). "Integrated data from TCGA and GTEx databases also indicated that highly abnormal changes of TREM1 expression in normal and cancer tissue." (PMID 39744496, 2025). "In combination with our current observations, inhibiting TREM1 can target its intrinsic expression in cancer cells and its extrinsic role in the TME." (PMID 40677705, 2025). "Further research is also warranted to elucidate the molecular mechanisms by which TREM1 regulates cancer stemness in HCC." (PMID 40677705, 2025). "Our research revealed the molecular conservation of TREM1+ PMN-MDSCs population across various cancers and their clinical prognostic value." (PMID 41413734, 2025). "Herein numerous studies have investigated the direct role of TREM1 in cancer cells, proving consistent observation of TREM1 protein expression in tumors and their cancer promoting role." (PMID 40677705, 2025). "Targeting TREM-1 signaling represents a promising therapeutic approach for managing a wide range of diseases, including cancer, neurodegenerative disorders, cardiovascular diseases, and other inflammation-driven conditions." (PMID 41226426, 2025). "This study is more focused on addressing the intrinsic role of TREM1 in cancer cells, separate from its well-established effects in TME." (PMID 40677705, 2025). "This highlights TREM1 as a potential biomarker, prognostic indicator, and treatment target in cancer care." (PMID 39149674, 2024). "Numerous studies have examined the relationship between TREM1 gene expression and cancer survival rates." (PMID 39149674, 2024). "This study utilized The Cancer Genome Atlas (TCGA) cohort to analyze the methylation and expression levels of TREM1 in cancers." (PMID 39149674, 2024). "In this study, we identified a significant relationship between hypomethylation and increased gene expression of TREM1 in the development of cancer." (PMID 39149674, 2024). "We observed a significant decrease in the promoter methylation level of TREM1, suggesting hypomethylation, in several cancers compared to normal samples." (PMID 39149674, 2024). "This study aims to analyze the promoter methylation level of TREM1 and its overexpression with cancer." (PMID 39149674, 2024). "We found that the IHC scores of DDX58 and TREM1 were higher in cancer tissues than in adjacent non‐cancerous tissues and the difference was significant." (PMID 38425247, 2024). "Promoter methylation analysis revealed that TREM1 is hypomethylated in cancers, resulting in significantly overexpressed mRNA across various cancer types." (PMID 39149674, 2024).
cancer (continued). "To further verify the reliability of our results, we selected two ICD‐related genes, DDX58 and TREM1, and collected cancer and adjacent non‐cancerous tissue specimens from 8 TNBC samples to detect the expression levels of DDX58 and TREM1 by IHC." (PMID 38425247, 2024). "In our study, we examined the correlation between promoter methylation and TREM1 gene expression across various cancers using the TCGA dataset." (PMID 39149674, 2024). "However, the underlying mechanism driving TREM1 mRNA expression in cancers remains unclear." (PMID 39149674, 2024). "In our study, we focused on the relationship between TREM1 gene expression and DNA methylation in cancer development." (PMID 39149674, 2024). "Studies conducted in vitro have demonstrated that inhibiting TREM1 can effectively impede the invasion of cancer cells." (PMID 39149674, 2024). "We found that TREM1 positively correlated with the infiltration levels of the immune cells, including monocytes and macrophages, across human cancers." (PMID 38370418, 2024). "Our work highlights the role of TREM1 in cancer progression, both intrinsically expressed in cancer cells and extrinsically in the TME." (PMID 37651197, 2023). "The oncomine database analysis revealed that TREM-1 was highly expressed in different types of cancer, including ccRCC." (PMID 37217993, 2023). "To better characterize the role of TREM1 expressed intrinsically in cancer cells, we established several stable HepG2 clones with confirmed TREM1 knockdown through RT-qPCR." (PMID 37651197, 2023). "Our observations highlight a dual role of TREM1 as an oncogene in cancer cells and an immunosuppressor gene in TME myeloid cells, suggesting that TREM1 has the potential to be a novel target for cancer treatment." (PMID 37651197, 2023). "Analysis of TCGA database revealed elevated TREM1 expression in numerous human carcinomas compared with normal tissue cells." (PMID 37651197, 2023). "Soluble TREM-1 level was significantly increased in patients suffering from HCC in comparison with those with non-malignant liver tumor/disease (ie: cyst, hemangioma, focal nodular hyperplasia) (p < 0.005)." (PMID 35875168, 2022). "Another potential role of TREM-1 concerns the regulation of apoptosis and autophagy, which play a double role in the regulation of senescence in normal and cancer stem cells, and of cellular responses to different therapeutical approaches." (PMID 35875168, 2022). "We next used the target gene panel to profile individual tumors and major cell types expressing TREM1, including myeloid cells, cancer cells and fibroblasts." (PMID 34956864, 2021). "Triggering receptor expressed on myeloid cells-1 (TREM-1) has been reported as a biomarker in many cancers." (PMID 34122331, 2021). "Consistent with the present report, these studies suggest a cross-talk between cancer and TREM-1 signalling in myeloid cells." (PMID 32908142, 2020). "Based on previous observations, we can infer that TREM-1 will be involved in cancer-prone environments of H. pylori infection and active inflammation." (PMID 32313120, 2020). "Currently, the crucial pathophysiological role of TREM-1 is defined not only in infectious diseases but also in both acute and chronic forms of aseptic inflammation as well as in different types of cancer." (PMID 32117302, 2020). "As previously outlined, since TREM-1 overexpression in the gut occurs only in pathological conditions, the involvement of this receptor in cancer onset is just secondary to inflammation, with resistance to cell death and induction of angiogenesis." (PMID 31546668, 2019). "Increasing evidence suggests a role for TREM-1 not only in acute pathogen-induced reactions but also in chronic and non-infectious inflammatory disorders, including various types of cancer." (PMID 29093489, 2017). "Clinical analysis indicated that the levels of TREM-1-related TAMs were significantly decreased during cancer stages progression." (PMID 27244892, 2016).